TYMS (thymidylate synthetase)
Diseases named in the same sentence as TYMS in open-access papers (continued):
Sharing a sentence is not in itself a finding about the gene and the disease.
colorectal cancer (continued). "The potential interplay or distinct impact of mutations within the EGFR pathway (EGFR, KRAS, NRAS, BRAF, PI3KCA), along with polymorphisms in genes related to 5-fluorouracil and oxaliplatin (DPYD, TYMS, GSTP1, MTHFR, ABCB1), on the prognosis of colorectal cancer remains uncharted territory." (PMID 38248103, 2024). "In accordance with the existing literature, NAA40 and TYMS were found to be elevated in colorectal cancer patients as opposed to normal colon tissues." (PMID 34785778, 2022). "We also evaluated the prognostic value of TYMS and BCL2L1 in colorectal cancer." (PMID 34141464, 2021). "Finally, we collected clinical samples to verify the expressions of TYMS and BCL2L1 in colorectal cancer." (PMID 34141464, 2021). "Nex, we studied TYMS and BCL2L1 expression levels in multiple colorectal cancer samples from TCGA, and the results showed that TYMS and BCL2L1 were markedly up-regulated in colorectal cancer patients than normal control." (PMID 34141464, 2021). "Therefore, in vivo and in vitro experiments were necessary to uncover the pathogenesis of TYMS and BCL2L1 of colorectal cancer in the future study." (PMID 34141464, 2021). "TYMS and BCL2L1 were significantly connected with the prognosis of colorectal cancer patients." (PMID 34141464, 2021). "In the current study, the mutation ratio of TYMS and BCL2L1 were small, and the development of colorectal cancer was not connected with TYMS and BCL2L1 genomic changes." (PMID 34141464, 2021). "Herein, TYMS and BCL2L1 were up-regulated in colorectal cancer patients in TCGA and GEO databases." (PMID 34141464, 2021). "TYMS expression was not related to overall survival of colorectal cancer or lung cancer patients, suggesting that MTHFD2 has a greater effect on prognosis than TYMS." (PMID 30582043, 2018). "The present study in line with other authors, has not confirmed that overexpression of TYMS protein or transcript predicts poor outcome in colorectal cancer patients." (PMID 27733154, 2016). "Moreover, TYMS is regulated by MYC, which affects PD-1 expression in colorectal cancer." (PMID 40642061, 2025). "However, another contemporary study has not confirmed these observations as intratumoral TYMS transcript level was not predictive in patients with colorectal cancer of stage II and III." (PMID 27733154, 2016). "However, down regulation of TYMS expression by these miRNAs did not sensitize cells to 5-FU in colorectal cancers." (PMID 23915286, 2013). "Finally, another mechanism of post-transcriptional regulation has been proposed in colorectal cancer cell lines (RKO, LoVo, DLD1 and SW620), where miRNA-192 and miRNA-195 modulate the expression levels of the TS protein without decreasing TYMS mRNA levels." (PMID 23056627, 2012).
colon carcinoma (58 papers, 1995 to 2026). "We also performed linear regression and identified a statistically significant (p = 0.0139) association between TYMS protein level and invasion potential of studied colon cancer cell lines and Snail-overexpressing cells." (PMID 35740289, 2022). "To address this question, we established the TYMS overexpressing colon cancer cells, and we have linked TYMS to EMT and metastasis induction." (PMID 35740289, 2022). "Since previous studies with TS-overexpressing colon cancer cells showed that elevated TYMS was associated with 5-FU resistance, but retained sensitivity to polymeric fluoropyrimidines (e.g., F10), we also tested CF10 in our SCLC PDO models." (PMID 32224870, 2020). "In this paper, we describe the first case of cardiomyopathy related to DPD deficiency and homozygous polymorphism of TYMS in a patient with colon cancer following 5-FU containing regimen." (PMID 27752409, 2016). "In addition, overexpression of TYMS is closely associated with an unfavorable prognosis for colon cancer, breast cancer, pancreatic cancer, cervical cancer, non-small cell lung cancer, and HCC patients." (PMID 35093082, 2022). "The present study showed that the expression of ABCC3, MTHFD2, and RFC‐1 was lower, and TYMS higher, in rectal compared to colon cancer." (PMID 40357991, 2025). "Because we recently reported that treating colon cancer cells with EPE modulates their invasiveness in a TYMS-dependent manner, we checked our extract’s influence in the MPM cells model." (PMID 37894370, 2023). "To verify this, we established preinvasive colon cancer cells stably overexpressing TYMS (LS180 TYMS cl 1 and LS180 TYMS cl 3)." (PMID 35740289, 2022). "Studies revealed that TYMS serves as a biomarker for colon cancer and breast cancers, and its overexpression promotes the growth, invasion, and metastasis." (PMID 35093082, 2022). "Then, we employed the Snail-overexpressing colon cancer cells to confirm that the TYMS protein level corresponds with invasive potency." (PMID 35740289, 2022). "Several miRNAs targeting TYMS mRNA have been identified in colon cancers, the levels of which can be regulated to varying degrees by lncRNAs." (PMID 35922756, 2022). "Then, we analyzed the TYMS protein level in the studied CRC panel and observed that the TYMS level correlates with the invasive potential of colon cancer cells." (PMID 35740289, 2022). "For TYMS in HCC, one possibility is that although TYMS mediates 5-FU resistance in colon cancer, it means nothing in HCC." (PMID 35093082, 2022). "Overall, our study showed a correlation between TYMS level and invasion ability in colon cancer cells and, above all, a crucial role of TYMS in the EMT regulation." (PMID 35740289, 2022). "We found that FOXM1 was highly correlated with tumor EMT, and previous studies suggested that FOXM1 regulated the expression of TYMS and mediated the resistance of tumor cells to 5-FU in colon cancer." (PMID 35093082, 2022). "Here, we report our studies on the role of TYMS in the modulation of invasive ability in colon cancer cells, where its effect on cancer metastasis is studied in detail." (PMID 35740289, 2022). "In summary, we established the role of TYMS in metastasis modulation of colon cancer cells through EMT stimulation." (PMID 35740289, 2022). "Firstly, we analyzed the panel of colon cancer cell lines with different invasion properties and found a correlation between TYMS protein level and cells’ invasion ability." (PMID 35740289, 2022). "This suggests a significant involvement of miR-1307-3p in the regulation of TYMS expression in at least some colon cancers." (PMID 35922756, 2022). "The phenomenon of TYMS copy number gain upon 5-FU administration in colon cancer patients has also been reported, suggesting the mechanistic approach behind acquired 5-FU resistance is through selective pressure." (PMID 34571731, 2021).
colon carcinoma (continued). "As a result, TYMS expression differences were only observed in colon cancer tissues and adjacent tissues (P < 1.00 × 10-4)." (PMID 33046972, 2020). "Elevated FOXM1 and TYMS expression was also observed in acquired 5-FU resistant colon cancer cells (HCT116 5-FU Res)." (PMID 30728402, 2019). "To conclude, in this study, we have demonstrated for the first time that FOXM1 has a crucial role in 5-FU drug resistance in colon cancer cells, through regulating some of the main 5-FU targets, including TYMS, TK-1 and TYMP." (PMID 30728402, 2019). "Overexpression and knock-down studies of FOXM1 in colon cancer cells suggest the importance of FOXM1 in TYMS regulation." (PMID 30728402, 2019). "Our findings show that rs7911488 C-allelic pre-miR-1307 leads to attenuated miR-1307-3p and elevated TYMS, thus insensitive to capecitabine chemotherapy in colon cancer." (PMID 29088787, 2017). "The TYMS genotypes predict TYMS mRNA expression, response and toxicity to 5-FU treatment in metastasized colon cancer." (PMID 29088787, 2017). "5-FU inhibits thymidylate synthetase and incorporates into both RNA and DNA, inducing intracellular increases in O2− levels in colon cancer." (PMID 28432271, 2017). "We show that increased HSP90 function after chronic exposure to 5-FU leads to Src activation, resulting in induction of genotypic and phenotypic changes involved in the EMT, induction of TYMS expression, and 5-FU resistance in colon cancer cells." (PMID 26416450, 2015). "This study was performed to investigate the mechanism by which TYMS expression is regulated and colon cancer cells become resistant to 5-FU." (PMID 26416450, 2015). "Here, we demonstrate that the enhanced HSP90 function and subsequent activation of Src induce expression of TYMS and acquired resistance to 5-FU in colon cancer." (PMID 26416450, 2015). "TYMS, which is involved in the metabolic process of 5-FU has been shown to mediate 5-FU resistance and predict prognosis of patients with colon cancer." (PMID 26416450, 2015). "EGFR (epidermal growth factor receptor) amplification, for instance, is a marker for gefitinib treatment and TYMS (thymidylate synthase) amplification conveys 5-fluorouracil resistance in colon tumors." (PMID 20398377, 2010). "Other studies revealed a tumor-stage-dependent upregulation of TYMS in colon cancer cell lines." (PMID 37894370, 2023). "Based on the in vitro studies demonstrating the ability of compound 19-S to inhibit TYMS catalytic activity and cause cytotoxicity in PDAC, PanNET, colon cancer, and SCLC cell lines, we studied the in vivo effects of compound 19-S in 2 xenograft tumor models available in our laboratory." (PMID 37097751, 2023). "We then hypothesized that C.B CM can improve the 5-FU chemo sensitivity in colon cancer cells by downregulating TYMS through the inhibition of MYC." (PMID 36941257, 2023). "Thus, we checked if TYMS would modulate cell invasiveness properties in colon cancer cells through the stimulation EMT process." (PMID 35740289, 2022). "We postulate that chemotherapeutics that decrease or inhibit TYMS expression could increase the effectiveness of the therapy in patients with colon cancer, especially in the metastatic stage." (PMID 35740289, 2022). "Thymidylate synthase (TYMS) is the crucial enzymatic precursor for DNA biosynthesis and, therefore, the critical target for numerous types of chemotherapy, including the most frequently applied agent in colon cancer treatment 5-fluorouracil (5-FU)." (PMID 35740289, 2022). "Since TYMS overexpression is often a consequence of using 5-FU chemotherapy in colon cancer treatment, we investigated whether TYMS silencing in TYMS-overexpressing cells would reverse the invasive phenotype." (PMID 35740289, 2022).
colon carcinoma (continued). "A further in-depth investigation is needed to verify whether TYMS inhibitor would abrogate the invasion properties of colon cancer cells and be able to reverse the EMT phenotype stimulated by 5-FU treatment." (PMID 35740289, 2022). "Indeed, the knockdown of TUG1 has demonstrated enhanced 5-FU chemosensitivity via the downregulation of TYMS expression in colon cancer cells." (PMID 34571731, 2021). "FP polymers such as CF10 may be more directly converted to FdUMP and thus display improved activity relative to 5-FU towards malignant cells that express elevated TYMS in TS-overexpressing colon cancer cells." (PMID 32224870, 2020). "TYMS was significantly overexpressed in SCLC relative to normal airway and the extent of overexpression (7.1-fold) is consistent with elevated TS levels that are associated with 5-FU-resistance in colon cancer." (PMID 32224870, 2020). "Patients’ characterization according to MMR status, CIMP phenotype and TYMS mRNA expression may provide a more tailored approach for adjuvant therapy in stage II colon cancer." (PMID 23446022, 2013). "Indeed, we observed that TYMS diminished could reverse the invasive phenotype in TYMS-overexpressing colon cancer cells." (PMID 35740289, 2022). "Therefore, we decided to check in the next step whether the TYMS itself would be able to stimulate EMT in colon cancer cells and, as a consequence, promote invasion ability and then metastasis phenotype." (PMID 35740289, 2022). "Hence, we demonstrated that TYMS stimulated the EMT phenotype in preinvasive colon cancer cells and increased the invasive potential of cells, in the next step, we investigated whether TYMS downregulation would inhibit these processes." (PMID 35740289, 2022). "The expression of TYMS can be suppressed by inhibiting the synthesis of hydrogen sulfide (H2S) and might be used as a potential therapeutic target to reverse the acquired resistance to 5-FU in colon cancer cells." (PMID 34393804, 2021). "The first three markers were chosen because they are involved in CRC tumorigenesis, whereas TYMS was analysed because it could be used to identify a subgroup of stage II colon cancer patients who better benefit from the use of adjuvant chemotherapy, as we pointed out in a previous study." (PMID 23446022, 2013). "Thus, TYMS may have prognostic value for patients with stage II colon cancer." (PMID 39998667, 2025). "In rectal cancer compared to colon cancer, ABCC3, RFC‐1, and MTHFD2 expression was significantly lower, while TYMS expression was higher." (PMID 40357991, 2025). "In human colon cancer cells, CASR activation downregulates expression of thymidylate synthase (TYMS), a key enzyme involved in DNA synthesis." (PMID 37377737, 2023). "Additionally, we studied whether TYMS overexpression would affect MMP-7, a small metalloproteinase known to be implicated in colon cancer development by decomposition of the extracellular matrix elements and basement membranes and activation of other MMPs such as proMMP-2 and proMMP-9." (PMID 35740289, 2022). "We employed colon cancer cells isolated from different stages of tumor development, cells undergoing EMT, and TYMS overexpressing cells." (PMID 35740289, 2022). "We observed that the TYMS silencing abolished the EMT process and inhibited the invasion of colon cancer cells." (PMID 35740289, 2022). "Upregulation of TWIST seems to increase the expression of both TYMS and DPYD, leading to 5-FU resistance in colon cancer cell lines." (PMID 33429840, 2021). "Moreover, 5-FU resistant colon cancer cells overexpressing TYMS exhibited several mesenchymal traits and expression of molecular markers indicative of an ongoing EMT process, which points out that activity of the EMT program may have an impact on TYMS expression." (PMID 33429840, 2021). "qPCR and Western blot were then used to check thymidylate synthase (TYMS), the direct target of 5-FU, and affected the sensitivity of colon cancer cells to 5-FU." (PMID 35071232, 2021).
colon carcinoma (continued). "We therefore decided to study the expression of FOXM1, TYMS, and E2F1 in colon cancer cell lines, following treatment with 2 μM of thiostrepton for 24, 48 and 72 hours." (PMID 30728402, 2019). "TYMS, SHMT2, GALT, RENBP, and AMDHD2 were among the metabolic genes that had an unfavorable expression in colon cancer, meaning that their high expression in patients treated with 5-FU was associated with poorer prognosis." (PMID 29026541, 2017). "To conclude, this study supports the contention that TYMS expression (at the mRNA level), dMMR and CIMP-High status are clinically relevant markers in patients with sporadic stage II colon cancer being considered for fluoropyrimidine-based adjuvant therapy." (PMID 23446022, 2013). "Further studies with higher power in sample sizes will be needed to deeply investigate the roles of TYMS expression, dMMR and CIMP status in patients with stage II colon cancer." (PMID 23446022, 2013). "Based on that knowledge, we decided to investigate the role of TYMS in the modulation of invasive ability in colon cancer cells, where its effect on cancer metastasis has not been studied in detail before." (PMID 35740289, 2022). "Interestingly, upregulation of TYMS and DTYMK was observed in the 5-FU resistant colon cancer cells." (PMID 29100421, 2017). "HCT116/R, a HCT116 colon cancer cell subline carrying acquired resistance to 5-FU, showed increased expression and activation of HSP90's client proteins and transcriptional up-regulation of TYMS." (PMID 26416450, 2015). "However, in this study, eupatilin did not have a significant effect on TYMS expression in colon cancer cells." (PMID 34203665, 2021). "We recognise that the relationship between TYMS, MMR, and CIMP in colon cancer could be complex." (PMID 23446022, 2013).